Y_RNA (Y RNA )
Gene: Miscellaneous RNA gene on chromosome 2 (55,286,018 to 55,286,128, forward strand). Ensembl gene ENSG00000206964.
Homologues: Orthologues: chimpanzee Y_RNA (100% identical), macaque Y_RNA (95% identical). Paralogues in human: RNY1 (88% identical), Y_RNA (87% identical), Y_RNA (86% identical), Y_RNA (85% identical), Y_RNA (84% identical), RNY1P10 (83% identical), RNY1P11 (83% identical), RNY1P7 (83% identical), Y_RNA (83% identical), RNY1P8 (82% identical), Y_RNA (82% identical), RNY1P5 (81% identical), and 95 more.